PPP1R2B (PPP1R2 family member B)
Description:
Inhibitor of protein-phosphatase 1.
Synonyms: PPP1R2P3; MGC87149
Tractability: PROTAC: ubiquitination databases record sites on it.
Gene: Protein-coding gene on chromosome 5 (156,850,295 to 156,852,528, forward strand). Ensembl gene ENSG00000231989.
Subcellular location (Human Protein Atlas): Nucleoplasm; Cytosol
Gene Ontology:
Molecular function: protein binding; protein phosphatase inhibitor activity
Biological process: intracellular signal transduction; regulation of signal transduction
Genetic constraint (gnomAD): Loss-of-function variants: 7 observed, 8.22 expected, observed/expected ratio (o/e) 0.85, 90% interval 0.48 to 1.57. That is too few expected variants to judge how well the gene tolerates losing a copy. Missense variants: 95 observed, 105.2 expected, observed/expected ratio (o/e) 0.9, 90% interval 0.76 to 1.07. Synonymous variants: 51 observed, 40.53 expected, observed/expected ratio (o/e) 1.26, 90% interval 1 to 1.59.
Homologues: Orthologues: chimpanzee PPP1R2B (98% identical), macaque PPP1R2 (97% identical), rabbit PPP1R2 (90% identical), rat Ppp1r2 (83% identical), dog PPP1R2 (83% identical), mouse Ppp1r2 (82% identical), mouse Ppp1r2-ps5 (80% identical), mouse Ppp1r2-ps1 (80% identical), mouse Ppp1r2-ps6 (80% identical), zebrafish ppp1r2 (55% identical), tropical clawed frog ppp1r2 (46% identical). Paralogues in human: PPP1R2 (96% identical), PPP1R2C (41% identical).